RAI2 (retinoic acid induced 2)
Diseases named in the same sentence as RAI2 in open-access papers (continued):
Sharing a sentence is not in itself a finding about the gene and the disease.
tumor (continued). "The same authors connected this event to the RAI2 promoter methylation, and suggest that RAI2 may serve as a tumor suppressor inducing cell apoptosis, and inhibiting cell migration acting as tumor suppressor by inhibiting the AKT signaling pathway." (PMID 32012980, 2020). "Hence, the potential antagonistic roles of RAI2 and CtBP as tumor suppressor and oncogene, respectively, could be explained through their ability to bind directly to each other." (PMID 38898011, 2024). "Furthermore, migration and invasion tests on Transwell suggested that RAI2 knockdown could considerably increase the migratory and invasive abilities of tumor cells." (PMID 37899172, 2023). "RAI2 may serve as a tumor suppressor by inhibiting the AKT signaling pathway in CRC." (PMID 29796120, 2018). "The average tumor volume was 105.09 ± 34.57 mm3 in RAI2 expressed RKO cell xenografts, and the average tumor volume was 1428.26 ± 566.46 mm3 in RAI2 unexpressed RKO cell xenografts." (PMID 29796120, 2018). "The expression levels of IGF2BP2, RAI2, SLC25A27, NCBP2, and EIF4B were greatly enhanced, as is the case in tumor development." (PMID 25978455, 2015). "RAI2 has been characterized as a potential metastasis suppressor protein that inhibits the dissemination of tumor cells to the bone marrow and when absent, induces an aggressive tumor phenotype in BC cells." (PMID 38898011, 2024). "Our results showed that high RAI2 expression could be regarded as an independent and favorable prognostic biomarker for BRCA patients, which predicts tumor invasion and metastasis." (PMID 37064084, 2023).
cancer (8 papers, 2018 to 2025). A tumor composed of atypical neoplastic, often pleomorphic cells that invade other tissues. "Among the 19 cases of cancer samples that had loss of/reduced expression of RAI2, 12 cases were methylated (63.15%)." (PMID 29796120, 2018). "These filaments lead to RAI2-mediated CtBP nuclear foci and relieve its corepressor function in RAI2-expressing cancer cells." (PMID 38898011, 2024). "In the current research, we relied on bio-informatics to examine the expression of RAI2 in pan-cancer and discovered that RAI2 was abnormally expressed in the majority of malignancies, including GC." (PMID 37899172, 2023). "In our previous study, the expression of RAI2 in 32 paired tissue samples was found reduced significantly in cancer tissue compared to the adjacent normal tissue by IHC detection." (PMID 35299743, 2022). "Retinoic acid-induced 2 (RAI2) has been recently identified as a transcriptional regulator that controls the expression of several key regulators in cancer." (PMID 33477997, 2021). "The expression of RAI2 was reduced significantly in cancer tissue compared to the adjacent normal tissue (P < 0.01)." (PMID 29796120, 2018). "The loss of RAI2 expression was found frequently in CRC cells, and the expression of RAI2 was reduced significantly in cancer tissue compared to the adjacent normal tissue samples." (PMID 29796120, 2018). "In contrast, in 13 cases of cancer tissue samples that expressed RAI2, only 3 cases were methylated (23.1%)." (PMID 29796120, 2018). "Taken together, these results suggest that the tumor suppressor RAI2 could be a potential target for the development of anti-cancer strategies in GC." (PMID 37899172, 2023). "There has only been one report addressing RAI2 in human cancers." (PMID 29796120, 2018). "Besides, there was a positive association between the increased RAI2 expression and luminal subtype of tumors rather than basal-like cancers (pooled OR = 6.95, 95% CI: 5.07–9.51, Cochran’s Q test, p = 0.39, and I2 = 4.6%)." (PMID 37064084, 2023). "We also investigated four genes, RAI2, KCNMA1, NBEA, and KIT, in the two ranking lists, and their potential functions for these two types of cancer." (PMID 31888440, 2019). "In our study, we found that RAI2 suppressed the expression of ASCL2 and LGR5 by Western blot in CRC cells, and we also found a negative correlation between RAI2 and ASCL2/LGR5 in 298 cases of cancer tissues from CRC patients by IHC detection." (PMID 35299743, 2022). "Then, we screened the expression of RAI2 in CRC cells and primary cancer samples." (PMID 29796120, 2018).
RAI2 also shares sentences with these, for which no sentence is quoted: prostate adenocarcinoma (2 papers); Alzheimer disease (1); Azoospermia (1); bladder urothelial carcinoma (1); Cirrhosis (1); colon adenocarcinoma (1); cryptorchidism (1); epilepsy (1); esophageal carcinoma (1); gastric cancer (1); glioblastoma (1); head and neck squamous cell carcinoma (1); hematologic malignancies (1); hepatocellular carcinoma (1); Intellectual disability (1); prostate tumor (1); schizophrenia (1); small cell lung carcinoma (1); stomach adenocarcinoma (1).